NGFR (nerve growth factor receptor)
Diseases named in the same sentence as NGFR in open-access papers (continued):
Sharing a sentence is not in itself a finding about the gene and the disease.
pancreatic cancer (24 papers, 2012 to 2025). "Additionally, NGFR may be involved in the perineural invasion of pancreatic cancer cells, mediating the chemoattraction of cancer cells for neural tissues." (PMID 40758712, 2025). "However, the exact role of NGFR in pancreatic cancer development is still unclear." (PMID 26294325, 2015).
glioblastoma (21 papers, 2008 to 2025). The most malignant astrocytic tumor (WHO grade IV). "Although the influence of NFGR inhibition remains to be explored, NGFR may serve as an alternative therapeutic target for glioblastoma." (PMID 35954323, 2022).
Anxiety (14 papers, 2015 to 2024). Intense feelings of nervousness, tension, or panic often arise in response to interpersonal stresses. "Loss of NGFR, which is a low-affinity receptor for BDNF and primarily expressed in basal forebrain cholinergic neurons, increases anxiety-like behavior in mice." (PMID 36834565, 2023). "NGFR signaling may interact with the cholinergic system to regulate anxiety-like behaviors and the acute stress response." (PMID 36834565, 2023). "We found that the serum levels of BDNF and T-cell expression of its receptor NGFR were elevated in patients with RA, and decreased serum BDNF levels were correlated with anxiety and biologics used in patients with RA." (PMID 33673283, 2021).
colorectal cancer (14 papers, 2011 to 2025). A primary or metastatic malignant neoplasm that affects the colon or rectum. "Consistent with our result, the deletion of NGFR protein in colorectal cancer is linked to a poor OS in people suffering from colorectal cancer, which is an independent predictor of the prognosis of colorectal cancer." (PMID 36518255, 2022). "Interaction of androgens with the nerve growth factor receptor NGF receptor affects colorectal cancer cells." (PMID 38115900, 2023). "NGFR enhanced chemosensitivity of colorectal cancer cells to 5-fluorouracil and increased 5-fluorouracil-induced apoptosis and autophagy." (PMID 35745143, 2022). "Yang and colleagues have shown that the NGFR expression is mainly down-regulated in colorectal cancer." (PMID 36518255, 2022). "More importantly, through the activation of S100A9, NGFR enhances the chemosensitivity of colorectal cancer cells by promoting the apoptotic and autophagic effects of 5-fluorouracil." (PMID 36518255, 2022).
Stroke (14 papers, 2012 to 2024). Sudden impairment of blood flow to a part of the brain due to occlusion or rupture of an artery to the brain. "NTRK2 (high affinity nerve growth factor receptor) is a receptor of BDNF that is also involved in neurogenesis and neuronal plasticity; this protein has been related to stroke throughout the pathway BDNF-TrKBPI3K/Akt." (PMID 35008673, 2021). "Genomic loci that are associated with increased stroke susceptibility and were reported by recent GWAS in European, non-Hispanic black and Hispanic ancestry samples do not include NGF and NGFR genes." (PMID 29499660, 2018).
schizophrenia (13 papers, 2012 to 2024). A major psychotic disorder characterized by abnormalities in the perception or expression of reality. "For the first time, our results indicate that the rs2072446 and rs11466162 polymorphisms in the NGFR gene are associated with schizophrenia in the Chinese Han population." (PMID 36291307, 2022). "It was reported that the NGFR SNPs rs11466155 and rs734194 were strongly associated with schizophrenia based on the Armenia Caucasus populations." (PMID 36291307, 2022). "In this study, we demonstrated a significant association between the NGFR gene (rs2072446 and rs11466162) and schizophrenia." (PMID 36291307, 2022). "Our results suggest that the NGFR gene is associated with schizophrenia in Chinese Han populations." (PMID 36291307, 2022). "In addition, an association between different NGF (rs6330, rs4839435) and NGFR (rrs11466155, rs2072446, rs734194) polymorphisms and schizophrenia were also found." (PMID 28358316, 2017). "We investigated four NGFR SNPs (rs1035050, rs575791, rs2072446, rs11466162) in 1010 patients with schizophrenia and 1034 healthy controls." (PMID 36291307, 2022). "Researchers found patients with schizophrenia and bipolar mania have lower levels of serum NGFR than healthy people, while MDD patients have higher results, which was led by NGFR polymorphisms." (PMID 36291307, 2022). "Decrease in NGF and NGF receptor (NGFR) blood levels was confirmed in drug-naïve schizophrenia patients and patients treated with haloperidol." (PMID 28358316, 2017). "Studies have shown significantly reduced brain-derived neurotrophic factor (BDNF), nerve growth factor (NGF), and NGF receptor (NGFR ) levels in the prefrontal cortex (PFC) and the cerebrospinal fluid (CSF) of subjects diagnosed with schizophrenia." (PMID 36979236, 2023).
hypopharyngeal carcinoma (11 papers, 2013 to 2025). Carcinoma, predominantly squamous cell, arising from the epithelial cells of the hypopharynx. "CD271 (also referred to as nerve growth factor receptor or p75NTR) is expressed on cancer stem cells in hypopharyngeal cancer (HPC) and regulates cell proliferation." (PMID 36273237, 2022).
gastric cancer (10 papers, 2017 to 2025). A primary or metastatic malignant neoplasm involving the stomach. "Similarly, a recent report has shown that the immunohistochemical expression of NGFR TrkA was associated with advanced clinicopathological factors of gastric carcinomas, such as lymph node metastasis and distant metastasis, and predicted shorter disease-specific survival and RFS." (PMID 28679437, 2017). "The expression of nerve growth factor receptor p75 (p75NTR) in gastric cancer cells is significantly lower than in adjacent tissues, suggesting that p75NTR may play a significant role in gastric cancer metastasis." (PMID 34485109, 2021).
lung carcinoma (10 papers, 2018 to 2025). "A previous study reported no NGFR expression was detected in lung cancer, but our results did not agree with this conclusion." (PMID 35745143, 2022). "Recent studies have shown several potential mechanisms related to the antiproliferative impact of RSV on lung cancer cells, including the binding of RSV to the Akt protein and destruction of the intracellular antioxidant pool in cells, in addition to the activation of the NGFR-AMPK-mTOR pathway." (PMID 39771566, 2024). "However, the role of NGFR in lung cancer has not been clarified." (PMID 35745143, 2022).
brain tumor (9 papers, 2008 to 2025). "NGFR+ cells infiltrated the brain tumor environment (BTE) and formed micrometastases in close proximity to MBM/BTE transition sites." (PMID 36435874, 2022).
Huntington disease (8 papers, 2017 to 2025). Huntington disease (HD) is a rare neurodegenerative disorder of the central nervous system characterized by unwanted choreatic movements, behavioral and psychiatric disturbances and dementia. "Studies have shown a strong link between NGFR and Huntington’s disease (HD), which is an inherited neurological disorder." (PMID 37714835, 2023).
cystitis (7 papers, 2013 to 2025). Inflammation of the urinary bladder. "Urothelial damage was a notable feature of all ketamine cystitis specimens and where urothelium remained, increased NGFR expression was observed, with expansion from a basal-restricted normal pattern of expression into the suprabasal urothelium." (PMID 24252413, 2013). "The NGFR+ lamina propria cells observed in ketamine cystitis were similar morphologically to myofibroblasts, but were negative for SMA in serial sections." (PMID 24252413, 2013). "In the ketamine cystitis patient group, 16 retained urothelium including intermediate cells and in 10 of these samples, expansion of intense basal NGFR expression into the intermediate compartment was observed." (PMID 24252413, 2013). "This study has also shown that the neurogenic changes seen in ketamine cystitis extend to the damaged urothelium, where increased expression of NGFR makes an unknown contribution to the pathology." (PMID 24252413, 2013). "Previous studies have reported increased Ki67 indices in ketamine cystitis urothelium and interpreted with the supra-basal NGFR+ expansion reported here, this might suggest changes in the epithelium towards a regenerative wound-healing phenotype." (PMID 24252413, 2013). "This histological study observed expansion of the basal NGFR+ labelling, stromal nerve hyperplasia and the occurrence of superficial neuroma-like lesions which likely contribute to the extreme bladder pain experienced by ketamine cystitis patients." (PMID 24252413, 2013). "NGFR+ labelling was abundant in the stroma of ketamine cystitis tissues with varying intensity which could not be directly associated with local urothelial loss." (PMID 24252413, 2013).
leukemia (7 papers, 2018 to 2025). A malignant (clonal) hematologic disorder, involving hematopoietic stem cells and characterized by the presence of primitive or atypical myeloid or lymphoid cells in the bone marrow and the blood. "Transduction efficiency (>90%) of donors cells was confirmed by expression of a truncated nerve growth factor (NGFR) protein co-expressed by the bi-cistronic retroviral vectors encoding ICN1 and leukemia was monitored in the blood of animals by flow cytometry." (PMID 40319015, 2025). "In this setting, both NGFR isoform-enriched CD19 CAR-T cell products induced leukemia remissions, as ascertained in peripheral blood and lymphoid organs." (PMID 29619024, 2018). "We, therefore, proceeded to test NGFR-enriched CD44v6 CAR-T cells in vivo against high-leukemia burdens by excluding those enriched through the NML isoform." (PMID 29619024, 2018). "To determine T-ALL burden in these animals, we enumerated leukemia cells in the bone marrow (BM), spleen, and peripheral blood by flow cytometry focusing on CD45.2+NGFR+ donor cells, which corresponded to ICN1-expressing cells." (PMID 38352301, 2024). "Most importantly, these cells could be tracked with anti-NGFR monoclonal antibodies in NSG mice, where they expanded, persisted, and exerted potent antitumor effects against both high leukemia and myeloma burdens." (PMID 29619024, 2018).
lymph node metastasis (7 papers, 2012 to 2025). "Notably, NGFR expression was significantly associated with a lack of lymph node metastasis and longer disease-free and overall survival of patients with high-grade basal-like ductal breast carcinomas." (PMID 40732340, 2025).
psoriasis (7 papers, 2016 to 2026). An autoimmune condition characterized by red, well-delineated plaques with silvery scales that are usually on the extensor surfaces and scalp. "The role of nerve growth factor in the pathogenesis of psoriasis is further supported by the evidence that inhibition of nerve growth factor receptor with either its blocker or its neutralizing antibody improves psoriasis." (PMID 40861201, 2025). "Moreover, in vivo experiments substantiated the pivotal role of NGFR in the mouse model of psoriasis." (PMID 40038877, 2025). "As neuropeptides have a role in the pathogenesis of both psoriasis and pruritus, increased expression of substance P receptor, high-affinity nerve growth factor receptor or calcitonin gene-related peptide receptor may be involved." (PMID 27716172, 2016).
colon cancer (6 papers, 2012 to 2023). "Depending on the context, NGFR expression can either be oncogenic or tumor suppressive and recent studies with colon cancer indicate it has anti-tumor activity." (PMID 26573568, 2015).
head and neck squamous cell carcinoma (6 papers, 2014 to 2022). A squamous cell carcinoma that arises from any of the following anatomic sites: lip and oral cavity, nasal cavity, paranasal sinuses, pharynx, larynx, and salivary glands. "NGFR has been identified as a marker of cells with these properties in multiple malignancies, including head and neck squamous cell carcinoma." (PMID 27683113, 2016). "This was further supported by data from head and neck squamous cell carcinoma (HNSCC) strengthening the link between NGFR expression and increased metastasis." (PMID 35693944, 2022). "As mentioned, NGFR is expressed not only in nervous tissue, but also in non-neuronal normal and cancer cells, such as head and neck squamous cell carcinoma and breast cancer, where it enhances proliferation and promotes cancer metastasis." (PMID 27683113, 2016).
medulloblastoma (6 papers, 2015 to 2025). A malignant, invasive embryonal neoplasm arising from the cerebellum. "Overall, inhibition PDGFA, CXCR4, BOC, MET, and NGFR have all shown therapeutic promise in SHH-subgroup medulloblastoma." (PMID 34667228, 2021). "NGFR (CD271) is a marker of SHH medulloblastoma, and CD271+ medulloblastoma cells exhibit increased Ras/MAPK signaling, invasion, and migration which can be successfully targeted with MEK inhibition." (PMID 34667228, 2021).
bipolar disorder (5 papers, 2014 to 2023). A disorder of the brain that causes unusual shifts in mood, energy, activity levels and the ability to carry out day-to-day tasks. "Interestingly, the expression of NGFR (nerve growth factor receptor) and several genes that have been implicated in the development of SZ, bipolar disorder (BD) and ASD were differentially expressed following HS." (PMID 24736721, 2014).
ischemic stroke (5 papers, 2013 to 2024). A stroke disorder caused by obstruction of blood flow to the brain, due to thrombotic (local blood clot formation) or embolic (due to a blood clot or other material traveling from another site) event. "In the present study, we evaluated the association of the functional polymorphisms in NGF (rs6330) and NGFR (rs2072446 and rs734194) genes with ischemic stroke in an Armenian population." (PMID 29499660, 2018). "In conclusion, our findings suggest that the NGF rs6330*T and NGFR rs2072446*T minor alleles might be nominated as a risk factor for developing ischemic stroke and NGFR rs734194*G minor allele as a protective against this disease at least in Armenian population." (PMID 29499660, 2018). "Previous studies demonstrated that altered presence of NGF and its receptor (NGFR) are linked to several important processes such as vascular hypertension, atherogenesis and inflammation which are considered to be risk factors for the development of ischemic stroke (IS)." (PMID 29499660, 2018).
peripheral nerve injury (5 papers, 2014 to 2024). Injury to a peripheral nerve. "The AMPK-mTOR signaling pathway is the downstream pathway of NGFR in Schwann cells, and it modulates autophagy at the early stage of peripheral nerve injury." (PMID 35745143, 2022). "Further evidence for this hypothesis comes from a study using a mouse model of peripheral nerve injury that showed strong up-regulation of NGFR by Schwann cells." (PMID 24498246, 2014). "Aging mouse SCs demonstrate reduced expression of nerve growth factor receptor (NGFR) as well as growth factors such as brain-derived neurotrophic growth factor (BDNF), which is, among other growth factors, important for functional recovery after peripheral nerve injury." (PMID 33213068, 2020).
sarcoma (5 papers, 2015 to 2024). A usually aggressive malignant neoplasm of the soft tissue or bone. "Three sarcoma lines (Rh30, SaOS2 and TC71) were transduced with a lentiviral vector carrying firefly luciferase (ffluc) and nerve growth factor receptor (NGFR) transgenes." (PMID 26173023, 2015). "The transduced sarcoma lines (Rh30-fflucN, SaOS2-fflucN, TC71-fflucN) were tested to confirm NGFR expression and were found to express a high-level of lucifearse activity." (PMID 26173023, 2015).
tauopathy (5 papers, 2019 to 2026). Neurodegenerative disorders involving deposition of abnormal tau protein isoforms (tau proteins) in neurons and glial cells in the brain. "Additionally, Tau pathology mouse models could be used to determine the long-term effects of neurogenesis and NGFR signaling on Tauopathies." (PMID 37429840, 2023).
amyloid (4 papers, 2014 to 2024). "Our study found that rs2072446 in NGFR is associated with both the risk of sAD in the Chinese Han population and the amyloid burden in the ADNI cohort, which reveals the role of p75NTR in AD from a genetic perspective." (PMID 36074475, 2022).
asthma (4 papers, 2017 to 2025). "NGFR (nerve growth factor receptor) and asthma: Nerve growth factor has been implicated in both the immune and neuronal components of allergic asthma pathogenesis." (PMID 36782330, 2023).
breast tumor (4 papers, 2014 to 2022). "The neurogenes APP and EFNB1 are upregulated in basal and HER2-enriched breast tumors meanwhile NGFR is upregulated only in basal-like breast tumors." (PMID 26673618, 2016). "In addition, the authors reported a downregulation and an upregulation of NGFR/p75NTR and TrkA, respectively, compared to primary breast tumors." (PMID 36354700, 2022).
Ewing sarcoma (4 papers, 2020 to 2024). A small round cell tumor that lacks morphologic, immunohistochemical, and electron microscopic evidence of neuroectodermal differentiation. "In a study done by Fanburg-Smith and Miettinen, non-neural mesenchymal tumors showed variable NGFR expression based on tumor type, with rhabdomyosarcoma demonstrating a 90% positivity of 94 cases, Ewing Sarcoma 32% in 31 cases and extraskeletal osteosarcomas 23% in 13 cases." (PMID 32821345, 2020).
hepatocellular carcinoma (4 papers, 2022 to 2024). A malignant tumor that arises from hepatocytes. "It has been demonstrated to attenuate cell growth by inhibiting glycolytic effects and acting as a miRNA sponge to interfere with NGFR expression in hepatocellular carcinoma (HCC)." (PMID 34782720, 2022). "This study suggests that the hepatitis B virus X protein (HBx) plays a significant role in the progression of hepatocellular carcinoma (HCC) and highlights the role of a protein called PTPN13, which is known to regulate FAS-induced apoptosis and NGFR-mediated proapoptotic signaling negatively." (PMID 37760479, 2023).
virus infection (4 papers, 2015 to 2024). "In addition, the multivariate analysis revealed NGF and NGFR levels, BMI scores, virus infection, and tumor stage as the independent risk factors for OS, DSS, DFI, and PFI." (PMID 38204220, 2024).
bladder cancer (3 papers, 2021 to 2023). "We identified three genes, PTHLH, BHMT2, and NGFR, involved in bladder cancer immunotherapy." (PMID 36439109, 2022). "Our results indicated that PTHLH, BHMT2, and NGFR might be novel targets for bladder cancer immunotherapy and prognosis." (PMID 36439109, 2022).
endometriosis (3 papers, 2018 to 2025). The growth of functional endometrial tissue in anatomic sites outside the uterine body. "NGFR expression was significantly upregulated in patient peritoneum (7.48, 7.10–7.89), peritoneal endometriosis (7.24, 6.88–7.66), and deep infiltrating endometriosis (6.99, 6.65–7.48) compared to control (6.47, 6.32–7.15) and patient endometrium (6.50, 6.36–6.59) (all p < 0.0001)." (PMID 41516088, 2025).
Hypertension (3 papers, 2012 to 2024). The presence of chronic increased pressure in the systemic arterial system. "Among the vascular risk factors (hypertension, type 2 DM, and hyperlipidemia), type 2 DM was the only factor significantly modifying the association between NGFR polymorphisms (rs2072446, rs741072, Hap2, and Hap5) and the risk of AD." (PMID 22236693, 2012).